NLRC4 (NLR family CARD domain containing 4)
Diseases named in the same sentence as NLRC4 in open-access papers (continued):
Sharing a sentence is not in itself a finding about the gene and the disease.
corneal ulcer (7 papers, 2013 to 2023). Area of epithelial tissue loss from corneal surface; associated with inflammatory cells in the cornea and anterior chamber. "In addition, S. pneumoniae and P. aeruginosa activate the NLRC4 inflammasome in corneal ulcers." (PMID 33149733, 2020). "Exploration of host immune response to bacterial infection has demonstrated elevated expression of the NLRC4 and NLRP3 inflammasomes in corneal ulcers of patients with infections due to Streptococcus pneumoniae and Pseudomonas aeruginosa." (PMID 34258050, 2021). "We found that neutrophils comprised >90% cells in corneal ulcers, and that there was elevated expression of TLR2, TLR4, TLR5 and TLR9, the NLRP3 and NLRC4 inflammasomes and the ASC adaptor molecule." (PMID 23750216, 2013).
cystic fibrosis (7 papers, 2018 to 2025). Autosomal recessive disorder caused by pathogenic variants in the CFTR gene (cystic fibrosis transmembrane conductance regulator), which encodes a chloride and bicarbonate channel expressed in epithelial cells, and follow the diagnosis criteria. "Previous research has found GG homozygote of rs212704 in NLRC4 was associated with A.fumigatus colonization in cystic fibrosis patients." (PMID 35407478, 2022). "For patients with cystic fibrosis, significant associations were found between A.fumigatus colonization and polymorphisms of NLRC4, including the haplotype ACTT (rs212704 rs455060 rs7562653 rs385076) and GG genotype of rs212704." (PMID 35407478, 2022). "A previous study has demonstrated that NLRC4 mediated IL-1R antagonist (IL-1Ra) through NF-κB to bind IL-1β, alleviating cystic fibrosis." (PMID 39052650, 2024). "Activation of the NLRC4 inflammasome is believed to contribute to high IL-1β production and pathogenicity in cystic fibrosis patients with chronic P. aeruginosa infection." (PMID 30062052, 2018). "Several lines of evidence also confirmed that NLRC4-derived IL-1Ra controlled NLRP3 activation by the ubiquitin/proteasomal degradation pathway in cystic fibrosis." (PMID 29692782, 2018). "The molecular mechanism by which NLRC4 inhibits NLRP3 inflammasome activity remains unknown, but clinical evidence confirms that a certain NLRC4 polymorphism is associated with increased risk of fungal colonization in cystic fibrosis patients and infection." (PMID 41249509, 2025). "Moreover, it is interesting to remember that loss-of-function SNVs in NLRC4 have been found in HIV patents with severe TB and in patients with cystic fibrosis affected by severe lung infections, reinforcing the important and poorly investigated role of NLRC4 in lung immunity and pulmonary diseases." (PMID 33193317, 2020). "Similarly, NLRC4 was found to contribute to the recognition and clearance of T3SS-expressing P. aeruginosa in a wound model, and in a cystic fibrosis lung model of infection." (PMID 36611990, 2023).
familial cold autoinflammatory syndrome 4 (7 papers, 2019 to 2025). Any familial cold autoinflammatory syndrome in which the cause of the disease is a mutation in the NLRC4 gene. "For example, NLRC4 gene mutations have been associated with familial cold autoinflammatory syndrome 4 (FCAS4), characterized by neonatal-onset, cold-induced urticarial rash and arthralgia." (PMID 34198614, 2021). "Since then, 14 pathogenic NLRC4 variants have been described, with clinical phenotypes ranging from AIFEC to familial cold autoinflammatory syndrome type 4 (FCAS4) and neonatal-onset multisystem inflammatory disease (NOMID)." (PMID 41116055, 2025). "NLRC4-associated macrophage activation syndrome (NLRC4-MAS) and familial cold autoinflammatory syndrome 4 (FCAS4) are part of NLRC4-AD." (PMID 31736939, 2019). "NLRC4 inflammasomopathy has varied phenotypes including autoinflammation and infantile enterocolitis (AIFEC) and familial cold autoinflammatory syndrome 4 (FCAS4)." (PMID 33042144, 2020). "In addition, there is another NLRC4-related SAID, which is familial cold autoinflammatory syndrome 4 (FCAS4)." (PMID 37250902, 2023).
lung carcinoma (7 papers, 2015 to 2024). "This loss of NLRC4 protein expression across tumor stages is consistent with a significant decrease at the gene expression level for COAD as well as lung cancers (LUAD and LUSC) (bulk tumor analysis from TCGA patient data set)." (PMID 38652550, 2024). "And from the risk model, we found that all of these factors were up-expressed in low-risk group, particularly, the level of NLRC4 in lung cancer was also significantly lower in the tumor sample." (PMID 36437954, 2022). "And the inflammasome activation assay initially validated that NLRC4 could promote IL-1β maturation, which leads to pyroptosis of lung cancer." (PMID 36437954, 2022). "Finally, gene expression profiles of non-small cell lung cancer showed that NLRC4 was down regulated in lung cancer tissue." (PMID 26378020, 2015). "Overall, we obtained higher correlations of those DC signatures with NLRC4 compared with TMEM73 expression in CRC and lung cancers." (PMID 38652550, 2024). "However, there are few studies on NLRC4 and NLRP1 in lung cancer, which need to be further studied." (PMID 36186792, 2022).
viral infection (7 papers, 2012 to 2026). "We identified a novel NLRC4 missense variant in one patient, potentially warranting further functional investigations of the role of NLRC4 in inflammatory responses to viral infection." (PMID 38231281, 2024). "Additionally, flagellin activates IL-22 and IL-18 activation through TLR5/NLRC4, driving IL-18-induced apoptosis of viral infection as well as IL-22-induced proliferation, thereby inhibiting viral infection." (PMID 35216425, 2022). "This comprehensive review synthesizes the diversified landscape of inflammasome activation during viral infections, extending beyond the canonical NLRP3 inflammasome to include specialized sensors such as NLRP6, NLRP9, NLRP1, NLRP12, and NLRC4." (PMID 42198749, 2026).
Alzheimer disease (6 papers, 2017 to 2025). A progressive, neurodegenerative disease characterized by loss of function and death of nerve cells in several areas of the brain leading to loss of cognitive function such as memory and language. "NLRC4 inflammasome induces neuroinflammation and contributes to memory impairment in Alzheimer's disease rats through the activation of caspase-1 and IL-1β." (PMID 33509083, 2021).
Arthritis (6 papers, 2019 to 2022). Inflammation of a joint. "Overexpressed NLRC4 in mice causes severe dermatitis, arthritis, and splenomegaly along with augmented neutrophil infiltration." (PMID 36457728, 2022). "Consistent with the role of mutated NLRC4 in the development of joint pathologies, transgenic mice expressing constitutively active NLRC4 produce high levels of IL-1β and IL-18, and develop arthritis." (PMID 31520179, 2019). "Two studies of antigen-induced murine arthritis show dependence on ASC, but caspase-1, NLRP3, and NLRC4 independence." (PMID 32366256, 2020).
asthma (5 papers, 2019 to 2025). "Hitherto, data availability is yet insufficient to assess a functional role of NLRC4 in asthma and awaits further evaluation." (PMID 36189256, 2022). "They include RBM42, STX5, and TRIM41 in asthma, CYP27A1, GM2A, LGALS9, SPI1, and NLRC4 in COPD, as well as ATF3, PPP1R15A, ZFP36, SOCS3, NAMPT, and GADD45B in IPF." (PMID 31952466, 2020). "These genes included RBM42, STX5, and TRIM41 in asthma, CYP27A1, GM2A, LGALS9, SPI1, and NLRC4 in COPD, ATF3, PPP1R15A, ZFP36, SOCS3, NAMPT, and GADD45B in IPF, LRRC48 and CETN2 in asthma-COPD, COL15A1, GIMAP6, and JAM2 in asthma-IPF and LMO7, TSPAN13, LAMA3, and ANXA3 in COPD-IPF." (PMID 31952466, 2020).
atherosclerosis (5 papers, 2020 to 2025). A disease characterized by the build-up of fatty material and calcium deposition in the arterial wall resulting in partial or complete occlusion of the arterial lumen. "NLRC4 is involved in the pathophysiology of atherosclerosis and myocardial infarction." (PMID 33584697, 2020). "We identified a set of genes (GSDMD, CASP1, NLRC4, AIM2, and IL18) closely related to atherosclerosis, particularly in atherosclerotic lesions with high pyroptosis scores." (PMID 38167983, 2024). "We used IHC to preliminarily detect the expression of GSDMD, CASP1, NLRC4, AIM2 and IL18 in advanced atherosclerosis plaques of patients." (PMID 38167983, 2024). "While NLRP3 is a key regulator of inflammasome activation, there is increasing evidence that other inflammasome sensors, such as NLRC4 and AIM2, also play a role in atherosclerosis." (PMID 37175869, 2023). "All other inflammasomes remain poorly understood in atherosclerosis, except AIM2, NLRP1, and NLRC4." (PMID 40564905, 2025).
cryopyrin-associated periodic syndrome (5 papers, 2018 to 2021). Cryopyrin associated periodic syndrome (CAPS) defines a group of autoinflammatory diseases, characterized by recurrent episodes of systemic inflammatory attacks in the absence of infection or autoimmune disease. "Gain-of-function mutations of NLRP3 and NLRC4 have been associated with autoimmune diseases which overlap in their symptoms, termed cryopyrin-associated periodic syndromes (CAPS)." (PMID 30042333, 2018). "The prevalence of organ-specific phenotypes (e.g., cutaneous phenotypes in NLRP1-associated syndromes) or cytokine-driven diseases (IL-18 in NLRC4-associated syndromes compared to IL-1 in NLRP3/Cryopyrin-Associated periodic Syndromes) may be largely due to differential transcriptional regulations." (PMID 33138274, 2020).
depression (5 papers, 2020 to 2025). "At the same time, phenolic metabolites represented by Malvidin have beneficial effects on anxiety and depression by targeting and regulating NLRP3, NLRC4 and AIM2 inflammasomes." (PMID 37474898, 2023). "The present study supports the role of MG to modulate NLRP3, NLRC4, and AIM2 inflammasome activation, both in primary cortical microglia and in a mouse model of anxiety and depression, as a potential therapeutic approach to addressing immune-inflammatory-based disorders." (PMID 35740286, 2022). "First, current studies on pyroptosis and neurological diseases are limited to NLRP3 and AIM2 inflammasomes, and the link between other types of pyroptosis-related inflammasomes, such as NLRC4, NLRP6, and depression, needs to be further investigated and elucidated." (PMID 35722622, 2022).
diabetic nephropathy (5 papers, 2016 to 2023). "Few microRNAs can promote pyroptosis progression in certain pathological processes by regulating NLRC4 to facilitate pyroptosis in diabetic nephropathy." (PMID 37142295, 2023). "Our previous research demonstrated that NOD-like receptor family CARD domain-containing protein 4 (NLRC4) inflammasome was overexpressed in renal tissues of patients with diabetic nephropathy (DN)." (PMID 35835791, 2022).
immune deficiency (5 papers, 2018 to 2025). "There has also been a report of activation of NLRC4 resulting in dampening of Toll-like receptor 5–induced antibody response to flagella, raising the possibility of an associated immunodeficiency." (PMID 29778503, 2018). "The detection of S paucimobilis in the CSF of patient P2 raises the question of an immunodeficiency associated with p.W655C NLRC4." (PMID 29778503, 2018).
liver fibrosis (5 papers, 2013 to 2024). "Mice with the A/J allele of Nlrc4 are resistant to hepatotoxin CCl4-induced liver fibrosis, therefore, we hypothesize that Nlrc4 may modulate the development of fibrosis." (PMID 26635450, 2015). "Though these studies show an important role of NLRC4 inflammasome in bacterial infection in liver cells, more studies are needed to explore the potential mechanisms of NLRC4 inflammasome activation and its role in liver fibrosis." (PMID 35707547, 2022). "Identifying the molecular mechanisms by which Nlrc4 modulates liver fibrosis is essential to fully understand the complex dynamics of liver disease origin and development." (PMID 26635450, 2015). "To determine if deletion of Nlrp3 or Nlrc4 influences known components in development of liver fibrosis, we measured α-SMA mRNA and hydroxyproline expression." (PMID 24453428, 2013). "In addition, it has also been reported that constitutive activation of the NLRC4 inflammasome to facilitate regeneration of liver cells and mitigate liver fibrosis after partial hepatectomy." (PMID 39052650, 2024). "We hypothesized that low-grade constitutive activation of the Nlrc4 inflammasome may lead to induced hepatocyte proliferation and prevent the development of hepatic fibrosis." (PMID 26635450, 2015). "Moreover, the NLRC4-driven IL-1 release was also involved in liver fibrosis." (PMID 35707547, 2022). "We have previously shown allelic differences of the Nlrc4 gene between inbred genetic mouse strains C57BL/6J (B6) and A/J modulate the development and/or resolution of hepatic fibrosis, a critical stage of NAFLD development." (PMID 26635450, 2015).
pneumonia (5 papers, 2019 to 2023). An acute, acute and chronic, or chronic inflammation focally or diffusely affecting the lung parenchyma, caused by an infection in one or both of the lungs (by bacteria, viruses, fungi, or mycoplasma.). "NLRC4 activation, on the other hand, causes inflammatory lung injury, increases lung bacterial burden, and causes necroptosis during P. aeruginosa-induced pneumonia." (PMID 34737734, 2021). "For example, activation of NLRC4 inflammasome in alveolar macrophage triggered by Pseudomonas aeruginosa causes impaired bacterial clearance and is associated with increased cell death and mortality in murine model of acute pneumonia." (PMID 34869331, 2021). "To evaluate the role of Neat1 on NLRC4 inflammasome activation in vivo, we used a mouse model of flagellin-induced pneumonia." (PMID 30940803, 2019). "Interestingly, during experimental pneumonia with Staphylococcus aureus, mice exhibit increased survival and reduced bacterial burden with NLRC4 ablation." (PMID 36829255, 2023). "Expression of NLRC4 is increased in both human and mouse lungs with pneumonia." (PMID 36829255, 2023). "Activation of NLRC4 stimulates the production of IL-1 β, IL-17A, and neutrophil chemoattractants in the lung, which prove beneficial to the host during pneumonia caused by Gram-negative bacteria such as K. pneumoniae and P. aeruginosa." (PMID 34737734, 2021). "Thus, NLRC4 deficiency in both hematopoietic and non-hematopoietic cells protects the host from S. aureus-induced pneumonia." (PMID 34737734, 2021). "Studies have also shown earlier, the protective action of mucosal (including sublingual root) flagellin administration to mice infected with S. pneumoniae-induced pneumonia without the activation of NLRC4 inflammasome." (PMID 32849610, 2020). "Thus, therapeutic targeting of NLRP3, NLRC4, and NLRP4 inflammasome during Gram-positive bacteria-induced severe pneumonia responsible for ALI may prove beneficial to the host." (PMID 32849610, 2020). "NLRC4 activation during Gram-negative bacterial (K. pneumoniae, P. aeruginosa) pneumonia proves beneficial to the host via producing IL-1β, IL-17A, and neutrophil chemoattractants (keratinocyte cell-derived chemokines, MIP-2, and LPS-induced CXC chemokines) in the lungs." (PMID 32849610, 2020).
AIDS (4 papers, 2018 to 2025). A syndrome resulting from the acquired deficiency of cellular immunity caused by the human immunodeficiency virus (HIV). "Besides its critical role in host defense against bacterial infections, NLRC4 was found to drive the development of a spectrum of autoinflammatory diseases (AIDs), collectively referred to as NLRC4-associated AIDs (NLRC4-AIDs) or NLRC4 inflammasomopathies." (PMID 38090573, 2023). "The literatures on NLRC4-AIDs were systematically reviewed, aiming to characterize the associated clinical features." (PMID 34248956, 2021). "Taken together, this study highlights the broad spectrum of clinical features and the severity of disease that can be seen in patients with NLRC4-AIDs." (PMID 29778503, 2018).
Autoimmunity (4 papers, 2021 to 2023). The occurrence of an immune reaction against the organism's own cells or tissues. "To date, the role of inflammasomes in autoimmunity have largely focused on NLRP3 and AIM2, but other inflammasome molecules such as NLRP1, and NLR family CARD domain-containing protein 4 (NLRC4) have also been implicated in autoimmunity." (PMID 37081890, 2023).
E. coli infection (4 papers, 2018 to 2022). "L. rhamnosus GR-1 inhibits activation of ASC-dependent NLRP3 and NLRC4 inflammasome activation and production of the downstream proinflammatory cytokines IL-lβ and IL-18 during E. coli infection." (PMID 30087667, 2018). "We provide evidence that L. rhamnosus GR-1 suppresses E. coli-induced ASC-dependent activation of NLRP3 and NLRC4 inflammasomes and thus decreases production of IL-lβ and IL-18 during E. coli infection." (PMID 30087667, 2018). "In contrast to NLRP3 activation in response to diverse stimuli, upon E. coli infection, NLRC4 responds to bacterial rod protein of the T3SS apparatus and flagellin." (PMID 30087667, 2018). "Western blot analysis demonstrated increased expression of NLRP3 and NLRC4 following E. coli infection, but this increase was attenuated by pre-incubation with L. rhamnosus GR-1, regardless of ASC knockout." (PMID 30087667, 2018). "Our data indicate that L. rhamnosus GR-1 suppresses activation of ASC-dependent NLRP3 and NLRC4 inflammasomes and production of downstream IL-lβ and IL-18 during E. coli infection." (PMID 30087667, 2018). "However, the contributions of the NLRC4 inflammasome to inflammatory responses that control E. coli infections are less clear in relation to L. rhamnosus GR-1." (PMID 30087667, 2018). "Compared with untreated control cells, expression of NLRC4 protein was elevated at 3 h after E. coli infection in WT cells only infected with E. coli (P = 0.027) but not in WT cells incubated with L. rhamnosus GR-1 alone or pre-incubated with L. rhamnosus GR-1." (PMID 30087667, 2018). "During E. coli infection in the present study, L. rhamnosus GR-1 decreased the secretion of IL-lβ and IL-18, in part due to suppression of ASC-dependent NLRC4 inflammasome activation." (PMID 30087667, 2018). "Furthermore, it was demonstrated that E. coli infection mediated the inflammatory response through activation of NLRP3 and NLRC4 inflammasome in bovine mammary epithelial cells." (PMID 35893774, 2022). "We hypothesized that during E. coli infection, the activity of NLRP3 and NLRC4 inflammasomes is differentially regulated by L. rhamnosus GR-1, inducing maturation of IL-1β and IL-18 or cell pyroptosis, depending on ASC." (PMID 30087667, 2018).
gram-negative bacterial infections (4 papers, 2016 to 2025). Infections caused by bacteria that show up as pink (negative) when treated by the gram-staining method. "The activation of the NLRC4 inflammasome could significantly impact gram-negative bacterial infections, particularly those linked to Salmonella typhimurium." (PMID 40028203, 2025). "Recruitment of the NLRC4 inflammasome may have a substantial effect on gram-negative bacterial infections, especially those associated with Salmonella typhimurium." (PMID 36765335, 2023). "In contrast to these protective roles of NLRC4 during several Gram-negative bacterial infections, NLRC4 can also contribute to pathogenesis." (PMID 33494299, 2021).
hemophagocytic lymphohistiocytosis (4 papers, 2022 to 2023). "The NLRP1 inflammasome was associated with myeloma and chronic myeloid leukemia, whereas NLRC4 was associated with hemophagocytic lymphohistiocytosis." (PMID 35897704, 2022). "Similar elevation of serum IL-18 and susceptibility to MAS/hemophagocytic lymphohistiocytosis (HLH) have been reported in monogenic diseases such as X-linked inhibitor of apoptosis deficiency (i.e., X-linked lymphoproliferative syndrome type 2) and NLRC4-associated autoinflammatory disease." (PMID 35958573, 2022).